CD68 (CD68 molecule)
Diseases named in the same sentence as CD68 in open-access papers (continued):
Sharing a sentence is not in itself a finding about the gene and the disease.
atherosclerosis (121 papers, 2009 to 2026). A disease characterized by the build-up of fatty material and calcium deposition in the arterial wall resulting in partial or complete occlusion of the arterial lumen. "This study successfully identified key genes associated with EndMT-related atherosclerosis, such as CD68, TLR2, MYD88, IRF7, STAT1, and IL1B, all of which demonstrate substantial diagnostic potential for detecting atherosclerotic plaques." (PMID 38268851, 2023). "The macrophage marker CD68 and Ly-6C have been used as an indicator of inflammatory reactions associated with atherosclerosis." (PMID 26180602, 2015). "The notion that monocyte migration is a key process in regression is supported by our transcriptional profiling data and immunohistological characteristics of atherosclerosis regression (loss of CD68-positive cells and decrease in Oil-Red-O staining)." (PMID 24586211, 2014). "In addition, the foam cells, the hallmark of atherosclerosis, within the atherosclerotic plaque were markedly reduced by wogonin, which was indicated by immunostaining with marker CD68." (PMID 40397286, 2025). "Additionally, the densities of CD20+ B- and CD4+ T-lymphocytes were associated with atherosclerosis- and inflammation-related changes, such as the accumulation of apolipoprotein B-100 and serum amyloid A, and densities of CD68+ and CD163+ macrophages." (PMID 40498464, 2025). "CD68, a common macrophage marker, is well-documented in its association with a variety of inflammatory diseases, further substantiating its relevance in the context of atherosclerosis." (PMID 38716195, 2024). "In advanced atherosclerosis, Vcam1 mRNA, encoding vascular cell adhesion molecule 1, was increased in the common carotids and Cd68, a highly expressed mRNA in macrophages, was increased in the carotid bifurcation, indicating that these sites were in different phases of atheroprogression." (PMID 38270847, 2024). "In summary, these results indicate that in a murine model of atherosclerosis inflammation resolution, antibiotic exposure impairs the loss of CD68-expressing foam cells from plaques, as well as altering them to an M1 state, with these changes independent of circulating cholesterol levels." (PMID 33903700, 2021). "Another recent study documented a high expression of CD68 by MYH11+ SMCs in the intima layer in the early stage of atherosclerosis in humans." (PMID 41301829, 2025). "Although plaque size remained similar to that in Apoe−/− donors, there was a 32% reduction in CD68+ macrophages, suggesting that antibiotics delay atherosclerosis inflammation resolution and that gut microbiota play a role in atherosclerosis inflammation." (PMID 40542540, 2025). "In both male and female mice, atherosclerosis regression markedly reduced CD68+CD38+ plaque area in the saline and trehalose groups." (PMID 38433753, 2024). "In our study, aortic CD45+ leukocytes and CD68+ macrophages significantly increased in arthritis mice combined with atherosclerosis and atherosclerosis mice." (PMID 39716053, 2024). "Leveraging machine learning algorithms, we have identified PLEK, IRF8, BTK, CCR1, and CD68 as evaluative markers to assist in the diagnosis of atherosclerosis." (PMID 38716195, 2024). "To provide targeted diagnostic assistance for atherosclerosis patients, we constructed a proprietary Nomogram model based on the expression of PLEK, IRF8, BTK, CCR1, and CD68." (PMID 38716195, 2024). "Arthritis mice combined with atherosclerosis (+ K/BxN serum + HFD) had most CD68+ macrophages infiltrated in aorta and intestinal, promoted the sustained inflammatory responses in aorta and intestinal." (PMID 39716053, 2024). "This study underscores the potential of CD68-Ce6-mediated liposomes as a promising nano-drug delivery system for atherosclerosis treatment, offering a viable alternative with enhanced specificity and efficacy." (PMID 38931851, 2024).
atherosclerosis (continued). "In agreement with an atherosclerosis-inducing action of T090317, the aortic arch CD68 mRNA expression levels were >5-fold higher (p < 0.001) in the T0901317-treated mice as compared to the controls." (PMID 38672446, 2024). "Our results showed that compared with arthritis mice (+ K/BxN serum −HFD), the aortic CD68+ macrophages significantly increased in arthritis mice combined with atherosclerosis (+ K/BxN serum + HFD) (P < 0.001)." (PMID 39716053, 2024). "Compared with tissues from WT mice at baseline, WT atherosclerotic tissues showed robust staining for CD68, a macrophage marker, supporting macrophage accumulation in the setting of atherosclerosis." (PMID 37991018, 2023). "Then we found that the colocalization of Unc5b, Fut8 and CD68 in the aortic sinus were strongly promoted during the development of atherosclerosis as indicated in the Development group." (PMID 36670464, 2023). "Atherosclerosis is characterized by infiltrating macrophages (CD68 positive cells) and an inflammatory response, which significantly affects the atherosclerotic disease status." (PMID 36736622, 2023). "Using immunofluorescence, expression of p-STAT3 was also repressed by IL-1β in CD68 + αSMA + cells, which were shown to accumulate in the plaque during atherosclerosis progression." (PMID 36456628, 2022). "Because the ETs release was reduced when PAD4 was inhibited in CD68+ VSMCs, we explored the effect of inhibition of CD68+ VSMCs generated ETs’ on the progression of atherosclerosis by using VSMCs-specific PAD4 conditional knockout (Myh11CrePad4flox/flox) mice." (PMID 36473863, 2022). "CD68 is a transmembrane protein that participates in oxidized low-density protein (OxLDL) clearance (e.g., lipid-laden foam cells in atherosclerosis) and is considered a pan-macrophage marker." (PMID 35526184, 2022). "Immunostaining of the lesions showed CD68 positive cells, thus represented macrophage-rich in HFD8w mice atherosclerosis lesions and vascular wall." (PMID 35145192, 2022). "ACA treatment also reduced the expression of atherosclerosis-related proteins, including CD68, α-SMA, ICAM-1, and TNFα, in the plaque area." (PMID 35563730, 2022). "This study seeks to investigate the interaction between CD68+ VSMCs and the formation of ETs and highlight its function in atherosclerosis." (PMID 36473863, 2022). "Next, to examine the possible effects of Dula on atherosclerosis, we evaluated plaque formation in the aortic arch and conducted immunohistological analyses of aortic root such as CD68, Mac-2 and Masson Trichrome staining." (PMID 33446799, 2021). "To further identify the origin of UBA1 expression, we costained UBA1 with CD68, a marker of macrophages, which is the main type and also majority of functional cells in atherosclerosis." (PMID 32258175, 2020). "Vcam-1 staining was markedly reduced with NMP treatment, and, consistent with this, macrophage infiltration into sites of atherosclerosis, as assessed with CD68 staining, was also significantly reduced." (PMID 32669659, 2020). "Monocytes and other leukocytes as well as proinflammatory cytokines participate pivotally in the various phases of atherosclerosis, and CD68 is a marker for macrophages." (PMID 32384892, 2020). "Intriguingly, some SMCs at the intimal hyperplasia were positive for CD68 and contained lipid depositions, indicating similarity with atherosclerosis." (PMID 32433495, 2020). "Since macrophages play a key role in the onset and progression of atherosclerosis, we then examined the accumulation of macrophages in the aorta using anti-CD68 antibody." (PMID 33195259, 2020). "Immunofluorescence staining also showed that the expression of vascular SMCs and CD68 were significantly increased in the atherosclerosis group (P < 0.05, P < 0.01)." (PMID 32213192, 2020). "Both atherosclerosis regression groups showed a significant decrease in lipid deposition and CD68+ macrophages compared to the baseline group." (PMID 31784656, 2019).
atherosclerosis (continued). "We have previously reported that Nox5 expression is significantly upregulated in atherosclerosis and is robustly expressed in the CD68+ Mac-rich area within human carotid artery atherosclerotic plaques." (PMID 31565149, 2019). "Having established that JAM-C blockade led to a greater reduction in plaque CD68+ cells in our mouse model of atherosclerosis regression, we investigated the distribution of JAM-C within the atherosclerotic plaques." (PMID 27442505, 2016). "Namely, oxLDL is stored in the PCAT and is supplied to the coronary intima either by CD68(+)-macrophages or vasa vasorum, and participate in atherosclerosis." (PMID 27010927, 2016). "To explore further the characteristics of atherosclerosis in llee mice, we quantified the macrophage infiltration by CD68 staining of the aortic sinus plaques (p<0.05)." (PMID 24489659, 2014). "To assess how changes in lesion composition after atherosclerosis regression alter plaque stability, we calculated a stability score: (SM22α+collagen areas)/(CD68+Oil-Red-O areas)." (PMID 24586211, 2014). "We found that a similar ∼50% reduction in atherosclerosis as assessed by CD68-stained macrophage accumulation in BaffR.ApoE DKO mice (p<0.05)." (PMID 22238605, 2012). "We have determined a molecular profile of atherosclerosis regression in a mouse transplant model by performing microarray analysis of plaque CD68+ cells." (PMID 22761902, 2012). "We previously reported in a transplant-based mouse model of atherosclerosis regression that the rapid depletion of plaque CD68+ cells was through a migration process dependent upon the induction of chemokine receptor CCR7." (PMID 22163030, 2011). "Exploitation of CD68’s known properties have already been shown to have therapeutic value in preclinical studies of atherosclerosis, and future studies using CD68−/− mice and their cells will hopefully shed light on new therapeutic opportunities." (PMID 21991369, 2011). "↑ M2 macrophages; ↓ CD68, improved cholesterol and triglyceride levels; ↓ Atherosclerosis." (PMID 41409275, 2025). "Additionally, immunohistochemical analysis using CD45 and CD68 markers confirmed the presence of an inflammatory response in the endothelial surface and the tunica adventitia during the phase of atherosclerosis with moderate lesions." (PMID 41301829, 2025). "We next examined plaque composition by focusing on two parameters commonly utilized as a surrogate indicators of atherosclerosis resolution: CD68+ area, a myeloid (macrophage) marker that represents plaque inflammation, and collagen area, a marker of plaque stability in humans." (PMID 38319073, 2024). "Gut microbiota-associated macrophage genes (PLEK, IRF8, CD68, CCR1, and BTK) may be implicated in the pathogenesis of atherosclerotic plaques and could serve as diagnostic markers to aid patients with atherosclerosis." (PMID 38716195, 2024). "To further investigate the potential role of gut microbiota-associated core macrophage genes in atherosclerosis, we applied unsupervised clustering methods based on the expression of PLEK, IRF8, BTK, CCR1, and CD68 to classify atherosclerosis patients into groups A and B." (PMID 38716195, 2024). "Additionally, we performed a pseudo-time developmental analysis of GSDME and macrophage marker CD68 to show the changes during the development of atherosclerosis." (PMID 36807553, 2023). "The specific mechanism of CD68 on atherosclerosis remain elusive but CD68-induced changes may relate to macrophage infiltration." (PMID 38268851, 2023). "The high CD68 showed high inflammation, which adversely affects the severity of atherosclerosis." (PMID 35324833, 2022). "Furthermore, we also find evidence that ETs generated from CD68+ VSMCs in three specimens from human aspiration atherosclerosis plaque and find that areas of ETs positive CD68+ VSMCs are related to MMP9 positive areas in a series adjacent section." (PMID 36473863, 2022).
atherosclerosis (continued). "By utilizing VSMCs-lineage tracing technology and single-cell RNA sequencing (scRNA-seq), we demonstrate that the ETs from CD68+ VSMCs influence the progress of atherosclerosis by regulating the direction of VSMCs’ transdifferentiation through STING-SOCS1 or TLR4 signaling pathway." (PMID 36473863, 2022). "Moreover, CD68 and CD163 are two macrophage-associated markers, whose expression levels are associated with adverse outcomes in human atherosclerosis." (PMID 34153003, 2021). "The agents that regulate CD68 expression and macrophage infiltration may determine in the progression or regression of atherosclerosis." (PMID 26305254, 2015). "In vivo administration of A-285222 completely blocked diabetes-induced NFAT-transcriptional activity in the aorta, leading to reduced expression of IL-6, OPN, MCP-1, ICAM-1, CD68 and TF, all established players in atherogenesis, as well as to reduced diabetes-induced atherosclerosis." (PMID 23755169, 2014). "Rare cells expressing FB-like (I-cluster 12, Pi16+, Igfbp4+, and Dpep1+) or MΦ-like genes (I-cluster 14, Lgals3+, Cd68+, and Ptprc+) had low expression of the eYFP lineage label, suggesting that these cells were not derived from VSMCs, similar to what has been proposed in atherosclerosis." (PMID 40577585, 2025). "Thus, expression of PHD proteins in CD68-rich regions in human plaque tissue suggests that PHDs may modulate atherosclerosis via the macrophage compartment." (PMID 33913468, 2022). "However, atherosclerosis, elastorrhexis, a large amount of CD68+ cell infiltration in the adventitia, and an obvious zone of CD68+ cell accumulation was observed at the interface between the adventitia and epicardial adipose tissue in samples from CAD patients." (PMID 21226932, 2011). "Compared to the control group, the Plut-treated group exhibited reduced CD68+ (macrophage) and MMP-9+ immunoreactive atherosclerosis, whereas the Dlut-treated group demonstrated the lowest macrophage infiltration and lowest MMP-9 expression among all cohorts." (PMID 40656542, 2025). "In a study conducted on 42 patients with atherosclerosis, gallium‐68‐labeled DOTATATE positron emission tomography (PET) was shown to be able to bind the SSTR2 on pro‐inflammatory CD68+ macrophages." (PMID 40789673, 2025). "The results indicated that compared with arthritis mice (+ K/BxN serum −HFD), arthritis mice combined with atherosclerosis (+ K/BxN serum + HFD) significantly increased the CD3+/CXCR3+ cells (P < 0.05), CD68+ macrophages (P < 0.001), CD3+ T cells (P < 0.05)." (PMID 39716053, 2024). "In atherosclerosis, CXCL4 drives the differentiation of M4 macrophages, which co-express CD68, MMP7, and S100A8." (PMID 39707183, 2024). "Immunohistochemistry of mouse and human atherosclerosis demonstrated higher levels of PIEZO1 protein in plaques, together with higher expression of CD68 positive monocytes and macrophage-like cells when compared with control artery." (PMID 39107572, 2024). "The results revealed that, compared to the ND group, the HFD group exhibited conspicuous co-localization of α-SMA+CD68+KLF4+, α-SMA+CD68+p-JAK2+, and α-SMA+CD68+p-STAT3+ at the foam cell aggregation regions of atherosclerosis plaque-rich aortic." (PMID 39062998, 2024). "Co-staining of GSDME and macrophage marker CD68 also showed that GSDME was localized in CD68-labeled macrophages, consistent with the results of human atherosclerosis single-cell analysis." (PMID 36807553, 2023).
atherosclerosis (continued). "Next, we analyzed the datasets (GSE43292, GSE12644, and GSE83453) obtained from aortas isolated from patients with atherosclerosis and stenosis for Cdon expression, together with aortic calcified markers such as Runx2, ALPL (alkaline phosphatase), and CD68." (PMID 36609601, 2023). "In a study identifying CD68+ cells as representing only macrophages, carotid 3-NT and NOSII co-localized in late stages of atherosclerosis, suggesting that NOS expression is involved in oxidation/peroxidation of lipids promoting carotid formation." (PMID 36911715, 2023). "In a similar manner to human atherosclerosis, BLVRB and its upstream enzyme in Hb catabolism, HMOX1, were also expressed in regions of CD68-positive macrophages in atherosclerotic mouse vein grafts." (PMID 37371462, 2023). "Moreover, we consistently observe that galectin-3 expression within CD68-positive cells (which we deem macrophages) is adversely diminished as plaques advance but are maintained in mouse plaque regression models, replicating observations in human atherosclerosis." (PMID 32295421, 2020). "We also measured levels of COX2, VCAM1, CD68, SM22, Bcl2 mRNAs and of atherosclerosis/inflammation -related miRs 21-5p, 125a-5p, 126-5p, 146-5p, 155-5p and 424-5p, to compare the inflammation and apoptosis levels among plaque material." (PMID 28472949, 2017). "HDAC7 appears to be upregulated in mouse models of atherosclerosis, consistent with the very low expression of CCR7 in CD68+ cells from atherosclerotic plaques." (PMID 22163030, 2011). "By conducting a correlation analysis of TG, TC and LDL with plaque area, necrotic core area and CD68+ area, it can be observed that IL-38 does not improve atherosclerosis by regulating lipid levels." (PMID 41463394, 2025). "In aged Apoe-/- mice, inhibition of NOX4 activity using GKT137831 significantly reduced macrophage mitochondrial ROS and improved mitochondrial function, resulting in decreased CD68+CD80+ and increased CD163+CD206+ lesion macrophage proportion and attenuated atherosclerosis." (PMID 38975335, 2024). "Here, as compared with UIAs without AWE, a higher aneurysm wall remodeling ratio (14/20 in UIAs without AWE, and 14/14 in UIAs with AWE), severer inflammation (CD68 and MMP2) and larger atherosclerosis area could be found in UIAs with AWE." (PMID 35155635, 2022). "PKC-δ was highly expressed in human atherosclerotic arteries infiltrated with TM and macrophages positive for CD68, suggesting that the interaction of macrophage tm-PKC-δ may participate in the formation of atherosclerosis." (PMID 35242825, 2022). "There were technical limitations of this study, such as that we were not able to co-stain GLP1R, ɑSMA and CD68 in the same human atherosclerosis specimens." (PMID 35401813, 2022). "In murine models assessing the impact of lipid lowering on atherosclerosis and inflammation resolution (e.g. reduction in CD68-expressing foam cells), plaques are not completely remodeled or reduced in size, even under optimal regression conditions." (PMID 33903700, 2021). "ApoE−/−FBXW2fl/flLysmCre+/− mice exhibited smaller lesions with fewer CD68+ plaque areas, suggesting that FBXW2 deletion in macrophages may alleviate progression of atherosclerosis in mice." (PMID 33101872, 2020). "MVPKOApoEKO mice suffered from larger lesions with more CD68+ plaque area, suggesting that MVP deletion may promote atherosclerosis in mice." (PMID 30996248, 2019). "CD68 which is known as scavenger receptor D has the ability to bind to oxidized low-density lipoproteins (LDL) and plays a major role in the development of atherosclerosis." (PMID 30356719, 2018). "Expression of the scavenger receptor CD68 is acquired by non-myeloid cells in the intima during atherosclerosis development." (PMID 29726984, 2018). "It therefore suggests that 11βHSD1-mediated regulation of inflammatory cell migration/infiltration is not likely to have a substantial effect on CD68 staining and atherosclerosis in this model." (PMID 23383297, 2013).